APP (amyloid beta precursor protein)
Diseases named in the same sentence as APP in open-access papers (continued):
Sharing a sentence is not in itself a finding about the gene and the disease.
Alzheimer disease (continued). "Active and passive immunotherapy in both amyloid-beta precursor protein (APP) transgenic mice and Alzheimer's Disease (AD) patients have resulted in remarkable reductions in amyloid plaque accumulation, although the degree of amyloid regression has been highly variable." (PMID 20929585, 2010). "Amyloid precursor protein binding protein-1 (APP-BP1) has been known to interact with the intracellular carboxyl (C-) terminus of the amyloid precursor protein (APP), the precursor protein of amyloid beta peptide (Aβ), which is the main component of neuritic plaques in Alzheimer's disease (AD)." (PMID 21151996, 2010). "Alzheimer's disease (AD) is a primary progressive neurodegenerative disease where the aberrant meta-bolism of the amyloid precursor protein (APP) and the production and deposition of beta-amyloid peptide (Aβ) are considered responsible for neuronal death." (PMID 20876941, 2010). "Indeed, in SOD1-related ALS, Huntington's disease, and Alzheimer's disease, specific neuronal subtypes are affected despite ubiquitous expression of SOD1, huntingtin and APP, respectively." (PMID 19266020, 2009). "The activation of the α-secretase pathway, that governs the non-amyloidogenic APP processing, represents one of the most important therapeutic targets for preventing and/or alleviating the Alzheimer's disease neuropathology." (PMID 18067682, 2007). "Amyloid precursor protein (APP on chromosome 21), presenilin I (PSEN1 on chromosome 14), and presenilin II (PSEN2 on chromosome 1) are all prominent early-onset Alzheimer's disease genes." (PMID 16515697, 2006). "Moreover, in the APP/PS1 mouse model of Alzheimer’s disease, HFD feeding increases nonheme iron overload in the hippocampus and cortex." (PMID 40819297, 2026). "Therefore, more disease-relevant Alzheimer’s disease models such as AppNL-F mice, that develop plaques gradually, with onset in older ages, and without APP overproduction were unable to produce sufficient plaque loads to influence bulk sequencing results." (PMID 39975899, 2025). "S100B and APP can be seemed to be multiple pathogenesis and co-occurrence of MS with DS and Alzheimer’s dementia may advance more severely than MS without DS." (PMID 40395918, 2025). "It has been reported that the splicing of the APP, APOE, SNCA, MAPT, DAO, SHANK3, and CACNA1C genes, which are recorded in the PsyGeNET database, were abnormal in patients with neurological diseases such as Parkinson’s disease, Alzheimer’s disease, and amyotrophic lateral sclerosis." (PMID 39858933, 2025). "They highlight the unique ability of APP among neurodegenerative disease-relevant substrates to be cleaved by CTSA and CTSH, and underscore the importance of systematically profiling these enzymes to better understand their potential roles in Alzheimer’s disease." (PMID 40671818, 2025). "Understanding the mechanisms of ONOO− reduction by the E2 domain of APP is crucial not only for expanding the scope and significance of copper proteins in ONOO− reduction but also for elucidating their physiological and pathological roles, particularly in the context of Alzheimer's disease." (PMID 39670805, 2025). "This suggests that an increased genetic load of APP, also observed in cases of familial Alzheimer’s disease, may contribute to the condition, although not in all cases." (PMID 40869138, 2025). "In addition, EGCG intervention in APP/PS1 transgenic rats, a commonly used model for studying Alzheimer’s disease, further showed that the expression levels of TLR4 and NF-κB were reduced after EGCG treatment, indicating that EGCG reduced the inflammatory response and decreased neurotoxicity." (PMID 39683391, 2024). "It was applied to mutant APPswe mRNA silencing without altering the wild-type APP mRNA in Alzheimer’s disease to show strong inhibition of pathologies while showing the power of silencing one “toxic” gene and expressing a second “protective” gene by a single AAV vector." (PMID 38972974, 2024).
Alzheimer disease (continued). "We explore the impact of WZ4003 in both wildtype and APP/PS1 cultures, to assess whether NUAK1 inhibition has differential impacts on models of Aβ pathology, partially replicating changes seen in Alzheimer’s disease, where dysregulated Aβ processing is thought to drive downstream changes to tau." (PMID 38175261, 2024). "Also, this is probably because most people had been interested in the generation of Aβ in Alzheimer's disease and believed that the increase in Aβ is due to increased generation from the amyloid precursor protein (APP) rather than decrease in degradation." (PMID 37882909, 2024). "However, it has not been revealed how HS diets accelerate the progress of Alzheimer’s disease (AD) in APP/PS1 mice." (PMID 39519278, 2024). "Previous study has found that an imbalance of APP may be involved with the negative correlation between cancer and Alzheimer's disease." (PMID 36925653, 2023). "Using neuronal cells expressing the wild type form of amyloid precursor protein (APP) infected by HSV-1, we characterized a representative cellular model of the early stage of the sporadic form of the disease and unraveled a molecular mechanism sustaining this HSV-1- Alzheimer’s disease interplay." (PMID 36898995, 2023). "For example, by processing Notch1 or the amyloid precursor protein (APP), γ-Secretase acts as a central player in developmental processes and dysregulation of the enzyme can lead to the development of devastating diseases including acute T-cell leukemia (T-ALL) and Alzheimer’s disease (AD)." (PMID 37261541, 2023). "Interestingly, this retraction is absent in the APP/PS1 mouse model of Alzheimer’s disease, supporting the concept that alterations in astrocyte-synapse coverage contribute to memory processing." (PMID 36779013, 2023). "In this study, we used APP/PS1 transgenic mice model that developed age-related accumulation of plaques and tangles in the brain, showing some relatable symptoms of Alzheimer’s disease to test the hypothesis that DHA is effective in treating Alzheimer’s disease." (PMID 35782939, 2022). "Indeed, the PLD3 - Phospholipase D3 is an important key in lipids metabolism and may be involved in the Amyloid Precursor Protein (APP), already been related to Alzheimer ́s Disease (AD)." (PMID 36046788, 2022). "In particular, overexpression of APP results in not only raised Aβ but also other APP metabolites, the levels of which may not be increased to any substantial degree in Alzheimer’s disease." (PMID 34266459, 2021). "APP multiple mutant mice without L-PGDS may be a new animal model of Alzheimer’s disease with early accumulation of Aβ plaques." (PMID 34744762, 2021). "Alternatively, one could speculate that the rearrangement may cause late-onset disease, explaining why the proband currently do not display any disease phenotype, an example being APP, which is involved in Alzheimer disease, a well-known late-onset disease." (PMID 33315133, 2021). "However, using the APPswe/PS1ΔE9 transgenic mouse model (APP/PS1), a classical model of Alzheimer’s disease expressing human APPswe that can readily be cleaved into Aβ in the hippocampus and cortex of mice, we were not able to detect Aβ monomers in retinal lysates at 5.5, 6 and 13 months of life." (PMID 34768774, 2021). "Besides, various gene mutations closely associated with mitochondrial function, including those involving amyloid precursor protein (APP), presenilin 1 (PSEN1), 46 presenilin 2 (PSEN2), apolipoprotein E (ApoE) and a disintegrin and 71 metalloprotease 10 (ADAM10), lead to Alzheimer’s disease." (PMID 33686350, 2021). "We used the APP/PS1 mice and 3 × Tg-AD mice model of Alzheimer’s Disease (AD) to further verify the improvement of brain function by TGL and found that Ganoderic acid A might be the effective constituent of TGL for anti-aging of the brain in the 3 × Tg-AD mice." (PMID 34025387, 2021).
Alzheimer disease (continued). "In Alzheimer's disease, BBR could be effective in decreasing the generation of the beta-amyloid (Aβ) peptide by APP processing in H4 human neuroglioma cells, and in inhibiting the activity of beta-site APP cleaving enzyme-1 (BACE-1) in a rabbit model of Alzheimer's disease." (PMID 32855766, 2020). "Our analysis identifies several well-known disease-related genes that are not identified by GWAS, including BRCA1 in Breast Cancer, Amyloid Precursor Protein (APP) in Alzheimer’s Disease, INS in A1C measurement and Type 2 Diabetes, and PCSK9 in LDL cholesterol, amongst others." (PMID 32678846, 2020). "In addition, lentiviral overexpression of miR-338-5p through intrahippocampal injection mitigated the amyloid plaque deposition and cognitive dysfunction in APP/PS1 mice, suggesting a protecting role of miR-338-5p against the development of Alzheimer’s disease." (PMID 33087587, 2020). "For example, for Alzheimer’s disease the activators or potentiators of ADAM10 activity might be useful to increase non-amyloidogenic processing of APP thus decreasing amyloid plaque formation in CNS." (PMID 32435655, 2020). "Chinese hamster ovary cells (CHO) stably transfected with amyloid precursor protein (APP) and presenilin 1 (PS1) and SAMP8 mice fed with high-fat diets (HFDs, known to induce metabolic stress, leading to cognitive impairment and aging) have been used to mimic Alzheimer’s disease." (PMID 32260305, 2020). "The amyloid precursor protein (APP) is expressed on nearly every cell type and the amyloid β (Aβ) peptides, which are generated by sequential cleavage of APP by the β- and γ-secretase, are known to aggregate to plaques in the brains of patients with Alzheimer's disease (AD)." (PMID 33013850, 2020). "APP, PSEN1, and PSEN2 gene testing was negative for mutations causing Alzheimer disease or CAA." (PMID 30597599, 2019). "During the last decade, proteolytic products of the amyloid precursor protein (APP) different from beta amyloid (Aβ) became the targets of Alzheimer’s disease (AD) research, as Aβ could not be proven to possess a decisive role in the AD pathomechanism." (PMID 31234498, 2019). "While our data largely support of the amyloid cascade hypothesis, the findings reported here indicate that a central component of Alzheimer’s disease pathology is the physiological function of APP rather than Aβ production per se." (PMID 30232325, 2018). "However, PLGA-PEG-B6/Cur nanoparticles could remarkably improve the cognitive impairment in APP/PS1 mice, which would be of potential use in Alzheimer’s disease." (PMID 30107760, 2018). "Also, eNOS-/- mice had increased amyloid precursor protein (APP), β-site APP-cleaving enzyme 1 (BACE1), and β-amyloid peptide (Aβ) in their brains compared to those of wild-type mice, which contribute to the pathogenesis of Alzheimer’s disease (AD)." (PMID 29896421, 2018). "ADAM10 is the main α-secretase that cleaves APP (amyloid precursor protein) in the non-amyloidogenic pathway inhibiting the formation of β-amyloid peptide, whose accumulation and aggregation leads to neuronal degeneration in Alzheimer’s disease (AD)." (PMID 29382156, 2018). "Also, it has been demonstrated that ciRS-7 can repress Alzheimer’s disease (AD) development by suppressing NF-κB protein synthesis and inducing its cytoplasmic localization, promoting UCHL1 expression and UCHL1-induced amyloid precursor protein (APP) and BACE1 ubiquitination and degradation." (PMID 30161026, 2018). "Therefore, if the third copy of the APP gene were eliminated in trisomy 21 cells of people with Down syndrome, then Aβ-induced aneuploidy, apoptosis, and possibly Alzheimer’s disease symptoms should not arise." (PMID 29516054, 2016). "We have recently identified in a transgenic mouse model of Alzheimer’s disease (AD) membrane-type 5-MMP (MT5-MMP) as a new player in Alzheimer’s pathogenesis, which displays pro-amyloidogenic features and proteolytic processing of amyloid precursor protein (APP)." (PMID 27349644, 2016).
Alzheimer disease (continued). "Besides finding the microRNAs that could regulate the critical nodes such as APP, BACE1, CD4, DCN, IL8 and PSEN1, we searched to uncover additional regulatory mechanisms of Alzheimer’s disease genes." (PMID 26784894, 2016). "Klotho is an amyloid precursor protein (APP)- and APP-like Protein 2 (APLP2)-dependent gene that is regulated by the large secreted ectodomain fragment soluble (APPsβ), and therefore, it may play a role in the development of Alzheimer’s disease." (PMID 26599613, 2015). "Changes in PAT1 expression in Alzheimer disease have not been yet investigated but could have consequences in APP signaling and cleavages." (PMID 25880931, 2015). "Interestingly, animals exposed to High or Low-DHA diets also exhibited differential Gpx4 transcriptional regulation in response to DHA-containing or DHA-impoverished diets and differentially affected between wild-type and APP/PS1, a familial model of Alzheimer's disease." (PMID 26257655, 2015). "Why the APP-sw-nucleofected PC-12 cells have nonfunctional modifications in cellular organelle essential for autophagy is not known, although numerous papers emphasize the importance of this process in pathogenesis of Alzheimer's disease." (PMID 25821818, 2015). "Interestingly, biochemical studies showed that IRP1 selectively regulates translation of amyloid precursor protein (APP) mRNA by binding to an atypical putative IRE motif, which may provide another connection of the IRE/IRP system with Alzheimer's disease." (PMID 25120486, 2014). "This may be due to the ability of EGCG to increase alpha secretase activity (the nonamyloidogenic pathway of APP processing) as discovered in a transgenic Alzheimer's disease mouse model." (PMID 24999480, 2014). "Finally, we examined whether G-CSF treatment enhances NEP activity and Aβ degradation using APP/PS1 Tg mice, a mouse model of Alzheimer's disease." (PMID 25062013, 2014). "In the same study, the cortical ferroxidase activity assigned to APP was reduced only in samples from Alzheimer's disease and not from Parkinson's disease; thus, the ferroxidase activity of APP in the basal ganglia in Parkinson's disease remains to be fully elucidated." (PMID 24672633, 2014). "The amyloid precursor protein (APP), a membrane protein with the ability to regulate synapse formation and repair has been widely studied for its role in Alzheimer's disease, but its role in other neurodegenerative diseases such as ALS continue to be discovered." (PMID 25177267, 2014). "APP blocker-9 (JTR-009), a benzimidazole, reduced the production of toxic Aβ in SH-SY5Y neuronal cells to a greater extent than other well tolerated APP 5′UTR-directed translation blockers, including posiphen, that were shown to limit amyloid burden in mouse models of Alzheimer's disease (AD)." (PMID 23935819, 2013). "Thus, evidence indicates that miR-153 contributes to post-transcriptional regulation of APP/APLP2 and may therefore have a role in Alzheimer's disease, although further validation of this potential interaction is required." (PMID 24133413, 2013). "In order to address this, Morales and collaborators carried out new transmissibility experiments in which wild-type human APP overexpressing transgenic mice that do not develop spontaneous amyloidogenesis were inoculated with human Alzheimer's disease brain extracts." (PMID 24187553, 2013). "Thus, we conclude that E2 or E1 domains of APP do not have ferroxidase activity and that the potential involvement of APP as a ferroxidase in the pathology of Alzheimer’s disease must be re-evaluated." (PMID 23977245, 2013). "Meprin β specifically cleaves in the N-terminal region of the amyloid precursor protein (APP), again at negatively charged amino acid residues, releasing two peptides that have been identified in the brain cerebrospinal fluid of patients with Alzheimer’s disease." (PMID 22940918, 2013).
Alzheimer disease (continued). "Previously we highlighted APP and Psen1 as good candidate modifiers in these regions since they have known links to Alzheimer's disease and Tau hyperphosphorylation, however, we did not detect significant differences in expression of APP or Psen1 between C57BL/6 and BALB/c samples." (PMID 22355340, 2012). "However, APP, Presenilin1/2, tau, Apolipoprotein E, Cdk5, TDP-43 or GSK-3beta, which are implicated in Alzheimer's disease and tauopathy, were not included in these results." (PMID 21731734, 2011). "These classes include products involved in APP signalling and processing (BACE1 and 2 and gamma-secretase components), cholesterol and lipoprotein function, tau function, inflammation, and oxidative stress, all of which are key processes disrupted in the Alzheimer's disease brain." (PMID 21234306, 2010). "Mechanistically, the authors report that MT5-MMP affect APP processing through proteolytic and non-proteolytic functions: MT5-MMP appears to promote the trafficking of APP towards the endolysosomal compartment which would lead to Aβ generation, a pathological hallmark of Alzheimer’s disease." (PMID 38992438, 2024). "In addition, overexpression of STMN2 in the hippocampus of an Alzheimer’s disease mouse model resulted in decreased amyloid β (Aβ) staining and plaque burden, presumably through STMN2-dependent regulation of the intracellular trafficking and processing of amyloid precursor protein (APP)." (PMID 37614226, 2023). "In the present study, we chose 4- and 12-month-old APP/PS1 mice to simulate mild AD and moderate AD, respectively, aiming to investigate whether EA could regulate the microglial polarization to modulate learning and memory at different stages of Alzheimer's disease." (PMID 32908486, 2020). "Alzheimer disease (AD) is characterized by senile plaques comprised primarily of β-amyloid (Aβ) and hyperphosphorylated tau in the form of neurofibrillary tangles; however, the largest AD GWAS have not shown a genetic signal in the regions of APP or MAPT in late-onset AD." (PMID 31261387, 2019). "Additionally, PSD-95 has been found to be downregulated by β-amyloid accumulation in amyloid precursor protein (APP)-mutant neurons, which is characteristic of Alzheimer’s disease, suggesting that the dysregulation of PSD-95 could be involved in Alzheimer’s disease pathogenesis." (PMID 30513696, 2018). "However, over the last decade, it has become clear that BACE1 not only cleaves APP but also has a number of other proteolytic substrates which are not known to be involved in the pathogenesis of Alzheimer’s disease but rather have other roles in the central nervous system." (PMID 27456313, 2016). "However, when studying late onset disorders it is frequently difficult to identify such families and by studying a large number of these families it seems more and more plausible that no other fully penetrant dominant genes like APP and the PSENs genes are to be found in Alzheimer’s disease." (PMID 25113539, 2014). "However, irrespective of the mechanism, the results suggest that APP signal transduction may be important in mediating Alzheimer's disease, at least in the transgenic mouse model, possibly downstream from Aβ oligomerization and binding of APP." (PMID 19558683, 2009). "By enhancing the non-amyloidogenic processing of amyloid precursor protein (APP) via increased α-secretase activity, SIRT1 reduces the production and accumulation of amyloid-β peptides, which are key pathological factors in Alzheimer’s disease." (PMID 41157743, 2025). "Although Ts21 neurons inherently overexpress amyloid precursor protein (APP) due to the presence of an extra copy of chromosome 21, this model does not fully replicate the natural progression of Alzheimer’s disease (AD)." (PMID 40244244, 2025). "Next, we assessed the transcriptome of genes of interest to Alzheimer’s disease and resistance, APOE, APP, MAPT, PSEN1, and RELN and found no notable differences across cell lines." (PMID 38571814, 2024).